E2F4 (E2F transcription factor 4)
Diseases named in the same sentence as E2F4 in open-access papers (continued):
Sharing a sentence is not in itself a finding about the gene and the disease.
cancer (continued). "Moreover, BIRC-5, KNTC-1, MCM2, MKI-67, PCNA, and E2F4 genes were downregulated in HCT-116 cancer cell lines, and there was no significant change in the expression of the same genes in HT-29 cancer cell lines." (PMID 40872562, 2025). "Our analysis identified E2F4 and TFDP1, two core components of the DREAM transcriptional repression complex, as transcriptional modulators preferentially activated by irinotecan in EPCAM+/CD44+/CD166+ as compared to EPCAM+/CD44neg/CD166neg cancer cells." (PMID 39896677, 2025). "However, the effects of E2F2, E2F4, E2F6, and E2F8 on prostate etiology and cancer growth are poorly understood." (PMID 37569304, 2023). "We identified and characterized a novel interaction of ΔNp73α with the E2F4/p130 transcriptional repressor complex that modulates the cellular gene expression in in vitro HPV38 E6/E7-transformed human keratinocytes (38HK), as well as in cancer-derived cells." (PMID 36883841, 2023). "As for the downregulated DEGs, the top TFs were E2F4/DP1, E2F1/DP2, E2F4/DP2, and E2F1/DP1, which are members of the E2F transcription factor family known to be involved in cell cycle control and cancer progression." (PMID 38057925, 2023). "An exception to this trend was observed in subcategories known for more severe, highly proliferative cancers, such as the basal and ER negative subtypes and high stage tumors, where the differences in E2F4 iRAS were less pronounced." (PMID 28464832, 2017). "A better understanding of the non-canonical roles and mechanisms for E2F4 will greatly benefit many fields, including stem cell and cancer biology." (PMID 27753528, 2016). "Similarly, we also saw DREAM-specific components both increase (eg E2F4) and to some extent, decrease (eg RBL2) across cancers." (PMID 25889361, 2015). "Moreover, the downstream effectors of KHDC4 and TRAF2 were observed to be positively correlated with E2F4, suggesting that E2F4, in addition to affecting KHDC4 and TRAF2 directly, indirectly influences their downstream regulators to participate in cancer malignancy." (PMID 40560737, 2025). "However, previous studies have not examined whether E2F4 binds to promoter regions to facilitate cancer cell growth and migration." (PMID 39309429, 2024). "Interestingly, E2F4 was a significant predictor of survival only in ER-positive and PR-positive and not ER-negative or PR-negative patients, suggesting that E2F4’s regulatory activity plays a role in steroid-dependent but not steroid-independent cancers." (PMID 25440089, 2014). "Thus, understanding the non-canonical functions of E2F4 will likely reveal novel insights into pluripotency and differentiation, which might in turn guide the development of strategies to block the expansion of cancer cells." (PMID 27753528, 2016).
infection (4 papers, 2022 to 2025). The state of being infected such as from the introduction of a foreign agent such as serum, vaccine, antigenic substance or organism. "We also observed a significant downregulation in the levels of phosphorylated p130 at Ser672, E2F4, and Cyclin A following infection." (PMID 40703674, 2025). "The labeled cells were then infected with sgRNA-expressing lentiviruses targeting Tfdp1, E2f4, or Rosa26, and analyzed one and three days post infection." (PMID 39043964, 2024). "In contrast, three days post infection, the mCherry+ cells containing sgRNAs against Tfdp1 and E2f4 showed a significant reduction in proliferation compared to control cells." (PMID 39043964, 2024). "Two other clusters showed lower, but still significant correlation with infection TF activity signature (Spearman’s rho = 0.14 and 0.18, p = 0.0122 and 0.00174, respectively), with prominent increase of STATs and decrease of E2F4 transcription factor activity." (PMID 35404937, 2022).
neurodegenerative disease (2 papers, 2022 to 2025). A disorder of the central nervous system characterized by gradual and progressive loss of neural tissue and neurologic function. "Since E2F4 is expressed in the nervous system, it may fulfill a crucial role in brain function and homeostasis, being a promising multifactorial target for neurodegenerative diseases and brain aging." (PMID 36292945, 2022). "Making an effort to better understand the non-canonical functions and mechanisms of action of E2F4 will greatly benefit many fields, including the study of neuronal function and malfunction associated with neurodegenerative diseases and brain aging." (PMID 36292945, 2022). "Therefore, E2F4 can be considered a multifactorial factor with an important impact on neuronal welfare and brain homeostasis, suggesting that it may be a promising candidate target for neurodegenerative diseases and brain aging." (PMID 36292945, 2022). "Finally, knocking down E2f4 using an E2f4-specific shRNA significantly decreased the protein levels of p-ERK, a key MAPK that has been involved in both neurodegenerative diseases, as well as in endocannabinoid and calcium signaling, which are critical pathways in synaptic function and modulation." (PMID 36292945, 2022).
blood cancers (1 paper, 2016). "This makes us to posit that the identified regions are regulatory sequences used for transcriptional control in normal tissues; some blood cancers potentially used these regulatory sequences for transcriptional activation, which were attached with E2F4." (PMID 27098038, 2016). "Although E2F4 was generally considered a transcriptional repressor, these data suggest that E2F4 may also contribute to transcriptional activation or bivalent regulation in blood cancers." (PMID 27098038, 2016).
neurological diseases (1 paper, 2022). "This suggests that E2F4 could be a promising target for several neurological diseases that course with synaptic plasticity impairment, such as AD." (PMID 36292945, 2022).
E2F4 also shares sentences with these, for which no sentence is quoted: bacterial infections (1 paper); brain cancer (1); CADASIL (1); carcinoma in situ (1); Cirrhosis (1); dementia (1); diabetes mellitus (1); diffuse large B-cell lymphoma (1); esophageal cancer (1); gastrointestinal tumors (1); hereditary hemochromatosis (1); kidney cancer (1); lentivirus infection (1); malignant neoplasm of the prostate (1); metastasis (1); metastatic cancer (1); myocardial infarction (1); nonalcoholic steatohepatitis (1); ovarian serous carcinoma (1); Parkinson disease (1); prion disease (1); prostate (1); psychiatric disorder (1); pulpitis (1); renal carcinoma (1); skin cancer (1); spinal cord injury (1); squamous cell lung carcinoma (1); sterility (1); viral infection (1).